PRG2 (proteoglycan 2, pro eosinophil major basic protein)
Description:
Cytotoxin and helminthotoxin. Also induces non-cytolytic histamine release from human basophils. Involved in antiparasitic defense mechanisms and immune hypersensitivity reactions. The proform acts as a proteinase inhibitor, reducing the activity of PAPPA.
Synonyms: BMPG; MBP; proMBP; MBP1
Tractability: Small molecule: a structure with a bound ligand is known. Antibody: UniProt places it where antibodies can reach, with high confidence; its Gene Ontology location is reachable by antibodies, with high confidence; UniProt predicts a signal peptide or a membrane-spanning region. PROTAC: ubiquitination databases record sites on it.
Gene: Protein-coding gene on chromosome 11 (57,386,780 to 57,391,143, reverse strand). Ensembl gene ENSG00000186652.
Subcellular location: Secreted (Bone marrow proteoglycan); Cytoplasmic vesicle, secretory vesicle (Eosinophil granule major basic protein)
Pathways (Reactome):
Immune System: Neutrophil degranulation
Gene Ontology:
Molecular function: extracellular matrix structural constituent conferring compression resistance; protein binding; carbohydrate binding
Biological process: immune response
Cellular component: extracellular exosome; extracellular matrix; extracellular region; ficolin-1-rich granule lumen; transport vesicle
Genetic constraint (gnomAD): Loss-of-function variants: 22 observed, 21.99 expected, observed/expected ratio (o/e) 1, 90% interval 0.71 to 1.43. The upper end of that interval is the gene's LOEUF score, 1.43, which puts it in group 5 of 6, group 1 being the genes least tolerant of losing a copy. Missense variants: 243 observed, 237.08 expected, observed/expected ratio (o/e) 1.02, 90% interval 0.92 to 1.14. Synonymous variants: 93 observed, 86.25 expected, observed/expected ratio (o/e) 1.08, 90% interval 0.91 to 1.28.
Homologues: Orthologues: chimpanzee PRG2 (99% identical), mouse Prg2 (60% identical), rat Prg2 (59% identical), guinea pig Large (53% identical), guinea pig Mbp2 (52% identical). Paralogues in human: PRG3 (48% identical).
Diseases named in the same sentence as PRG2 in open-access papers:
PRG2 is named in the same sentence as 36 diseases in open-access papers, as found by Europe PMC text mining. Sharing a sentence is not in itself a finding about the gene and the disease. The quoted sentences say what the papers report.
asthma (10 papers, 2014 to 2024). "The most interesting of these findings involved two genes (EPX and PRG2) in the KEGG pathway for asthma (Benjamini P-value = 0.00056) and associated with the eosinophils annotation (Benjamini P-value = 0.0087)." (PMID 26292806, 2015). "Discovered DMRs annotated to genes implicated in allergy and asthma, Th2 activation and eosinophilia (EPX, IL4, IL13, PRG2, CLC and ZFMP1) and genes previously associated with asthma and IgE in an EWAS of blood (ACOT7, SLC25A25)." (PMID 35344303, 2022). "Many of the methylation sites we identified have been associated with asthma including ADAM19, EPX, IL4, IL5RA, and PRG2." (PMID 29692868, 2018). "Several of these methylation loci were previously associated with asthma (ADAM19, EPX, IL4, IL5RA, and PRG2)." (PMID 29692868, 2018). "Specifically, we identified multiple methylation loci in genes previously associated with asthma (ADAM19, EPX, IL4, IL5RA, and PRG2) from genome-wide and epigenome-wide association studies." (PMID 29692868, 2018). "The functional annotation results implicated the genes EPX and PRG2 in eosinophil activity and in the KEGG pathway for late hypersensitive responses in asthma." (PMID 26292806, 2015). "Functional gene categories represented in DMRs and individual CpGs found for FeNO, asthma, and allergy were eosinophilic activity (EPX, CLC, PRG2), and Th2 responses (IL-4, ZFPM1)." (PMID 31300640, 2019). "None of the ABRIDGE modules met this threshold, and values of prg1, prg2 ≤ 0.05 for all of the five top modules indicate that the intra-module correlations are non-zero for patients with both better and worse asthma control." (PMID 37275375, 2023).
airway hyperresponsiveness (4 papers, 2017 to 2024). "Of those dysregulated genes, four were associated with immune-mediated inflammatory diseases (Csf2; Crlf2; Rnase2b; Tpsb2) and one with airway hyperresponsiveness (Prg2), while Il-13 was associated with both of those pathways." (PMID 36834405, 2023).
Obesity (2 papers, 2017 to 2023). Accumulation of substantial excess body fat. "Especially interesting and promising target molecules for obesity-derived implications in placenta could be CCL2, PRL, MMP12, TAC3, PRG2 and IGFBP1 that were the most dysregulated genes among our study group." (PMID 28125591, 2017).
acute myeloid leukemia (1 paper, 2021). Acute myeloid leukemia (AML) is a group of neoplasms arising from precursor cells committed to the myeloid cell-line differentiation. "FMR1 is shown to have regulated histone methylation H4K27m3 in lymphoblastoid and fibroblast cell lines while PRG2 has been discerned to get hypomethylated in acute myeloid leukemia." (PMID 34788504, 2021).
allergic asthma (1 paper, 2019). A asthma with a basis in a pathological type I hypersensitivity reaction. "Lower DNAm of PRG2, which encodes for a pro-eosinophil major basic protein, was associated with FeNO and allergic asthma." (PMID 31300640, 2019).
Alzheimer disease (1 paper, 2017). A progressive, neurodegenerative disease characterized by loss of function and death of nerve cells in several areas of the brain leading to loss of cognitive function such as memory and language. "This cell-based litmus gene assay identified six genes (CCL20, CEMIP, IL1B, IL8, PRG2, PTGS2) as potential biomarkers of plasma quality control and the SPC25 gene as a diagnostic biomarker of Alzheimer’s disease (AD)." (PMID 29203810, 2017).
chronic myeloid leukemia (1 paper, 2024). "Additionally, low PRG2 expression has been associated with drug resistance in chronic myeloid leukemia." (PMID 39339686, 2024).
Cirrhosis (1 paper, 2016). A chronic disorder of the liver in which liver tissue becomes scarred and is partially replaced by regenerative nodules and fibrotic tissue resulting in loss of liver function. "Proteoglycan expression revealed the up-regulation of LUM and PRG2, while the abundance levels of BGN, that showed a gradual decrease during fibrosis progression, were found underexpressed up to 12 times in cirrhosis." (PMID 26998606, 2016).
dengue (1 paper, 2025). "The identified DEPs, such as STXBP5, THBS1, and PRG2, have potential as biomarkers for predicting severe dengue outcomes." (PMID 41583452, 2025).
hearing loss (1 paper, 2022). "Finally, two genes, Ptgs1 and Prg2, are associated with inflammatory responses but not previously associated with hearing loss." (PMID 35454087, 2022).
Hydrocephalus (1 paper, 2022). Hydrocephalus is an active distension of the ventricular system of the brain resulting from inadequate passage of CSF from its point of production within the cerebral ventricles to its point of absorption into the systemic circulation. "PRG2, MMP12, and COX4I1 are related to neurological function, and previous studies proved that MMPs were biomakers of BM; however, these proteins were not significantly differed between the hydrocephalus group and healthy groups in our study." (PMID 36052359, 2022).
hypereosinophilic syndrome (1 paper, 2025). Hypereosinophilic syndrome (HES) constitutes a rare and heterogeneous group of disorders, defined as persistent and marked blood eosinophilia and/or tissue eosinophilia associated with a wide range of clinical manifestations reflecting eosinophil-induced tissue/organ damage. "While PRG2 had not been previously related to RA, it had been associated with hypereosinophilic syndrome." (PMID 40781639, 2025).
melanoma (1 paper, 2025). A malignant, usually aggressive tumor composed of atypical, neoplastic melanocytes. "Furthermore, differential expression analysis revealed upregulation of genes such as PTK2, PRG2, and VEGFA in tumor samples compared to normal skin, alongside downregulation of other ARGs—reinforcing their involvement in melanoma pathogenesis." (PMID 40943183, 2025).
multiple myeloma (1 paper, 2022). "Moreover, we found that YY1 mutation could affect the expression changes of certain genes in some cancers; for example, in multiple myeloma, YY1 mutation could affect the expressions of ERMN, DUSP8, PRG2, BMF, and RNASE2 genes." (PMID 35791393, 2022).
pancreatic cancer (1 paper, 2015). "However, epigenetic silencing of PRG2 is associated with higher proliferation and lowered apoptosis in pancreatic cancer cells and leukemic cells." (PMID 26547689, 2015).
tumor (7 papers, 2015 to 2025). "Since PRG2 plays a tumor suppressor function, and PRG4 shows an anti-inflammatory role, the downregulation of these proteoglycans in the cancerous ECM have been additional investigated by IHC analysis in paired samples, and confirm the results obtained from the proteomics analysis." (PMID 31687002, 2019). "A number of fast evolving, placental genes show tumorigenic or tumor suppression activity (ADAM12, ADAMTS18, CAPN6, EGFL6, HTRA4, LIN28B) and others are involved in disorders associated with epithelial and connective tissues (FBN2) or have immune functions (IL1RL1, PRG2, SIGLEC6)." (PMID 26641094, 2015). "By proteomics approach, we observed that ECM components known to have tumor suppressor functions and anti-proliferative effects (i.e.: INHBE and PRG2) were found strongly downregulated in iCCA." (PMID 31687002, 2019). "This correlation suggests that in the Basal subtype, LINC02188 may enhance the release of tumor angiogenesis factors (TNFRSF21, PRG2) by augmenting RNA methylation, consequently promoting angiogenesis." (PMID 38408075, 2024). "Notably, there was a positive association between the levels of ARGs and CNV alteration; for example, the expression levels of PRG2, SERPINA5, and THBD were low in tumor tissues, while VEGFA, PF4, and PTK2 were expressed at high levels." (PMID 37938164, 2023).
infection (6 papers, 2013 to 2025). The state of being infected such as from the introduction of a foreign agent such as serum, vaccine, antigenic substance or organism. "Notably, rnp-6 RNAi promoted the splicing of prg-2 intron-1, which shows the same trend as seen during infection and is largely inhibited by the G281D mutation." (PMID 32538777, 2020). "Some up-regulated genes at 21 dpi (e.g., Ltf, Cxcl9, Pglyrp1, Prg2, Cxcl13, Cxcl3, Ccl9, Ccl19, Krt5, Krt14, Krt15, Krt17, and Slpi) were also identified in a previous infection study by using H1N1(PR8)." (PMID 38005876, 2023). "Splicing of prg-2 and tos-1, which exhibited rnp-6 G281D dependent splicing remodeling upon infection, was also affected by rnp-6 RNAi, whereas gyg-1 had no detectable changes." (PMID 32538777, 2020). "Bone marrow proteoglycan 2 (Prg2), inter-alpha-trypsin inhibitor heavy chain H3 (Itih3), and three fibrinogen proteins (Fga, Fgb, Fgg) showed similar patterns of abundance with elevated levels during infection over time." (PMID 41061967, 2025).
cancer (5 papers, 2015 to 2022). A tumor composed of atypical neoplastic, often pleomorphic cells that invade other tissues. "Bone marrow proteoglycan 2 (PRG2) has been shown to be suppressed in cancer, has antiinflammatory roles, and is lower in fibrotic alveoli." (PMID 35852874, 2022). "Aberrant methylation of tumor suppressor genes (TSG) such as SOCS-1, SOCS-3, SHP-1, and PRG2 has been documented in a variety of cancers including hematological malignancies, and is a plausible means by which cells can acquire therapy resistance." (PMID 26547689, 2015). "There are 10 highly significant, direct and physical associators with a confidence score of ≥5.0 namely – RELA, HMOX2, EZH2, p-10Y-ERBB3-1, WDR1, ERRFI1, PRG2, FMR1, DEFA6-(?-100), cytf_human and the majority of the network associators of POTEE are epigenetically activated in many cancers." (PMID 34788504, 2021).
inflammation (1 paper, 2018). Aberrant reaction of the microcirculation characterized by movement of fluid and leukocytes from the blood into extravascular tissues. "IL4 and IL5RA are well-characterized cytokines responsible for Th2 cell differentiation and effector function, ADAM19 is involved in airway and vasculature remodeling, and PRG2 and EPX are both eosinophil-related proteins that play key roles in eosinophil-related airway inflammation." (PMID 29692868, 2018).
PRG2 also shares sentences with these, for which no sentence is quoted: eosinophilia (4 papers); Allergy (3); Down syndrome (2); Achalasia (1); allergic rhinitis (1); atopic dermatitis (1); Crohn disease (1); diabetes (1); Erythema (1); Granuloma (1); hematological malignancies (1); intrauterine growth restriction (1); lung diseases (1); osteoarthritis (1); placental disorders (1); rheumatoid arthritis (1); uterine cancer (1).